HIF1AN (hypoxia inducible factor 1 subunit alpha inhibitor)
Description:
Hydroxylates HIF-1 alpha at 'Asn-803' in the C-terminal transactivation domain (CAD). Functions as an oxygen sensor and, under normoxic conditions, the hydroxylation prevents interaction of HIF-1 with transcriptional coactivators including Cbp/p300-interacting transactivator. Involved in transcriptional repression through interaction with HIF1A, VHL and histone deacetylases. Hydroxylates specific Asn residues within ankyrin repeat domains (ARD) of NFKB1, NFKBIA, NOTCH1, ASB4, PPP1R12A and several other ARD-containing proteins. Also hydroxylates Asp and His residues within ARDs of ANK1 and TNKS2, respectively. Negatively regulates NOTCH1 activity, accelerating myogenic differentiation. Positively regulates ASB4 activity, promoting vascular differentiation.
Synonyms: FIH1; FLJ20615; DKFZp762F1811; FLJ22027
Tractability: Small molecule: a structure with a bound ligand is known; it has a high-quality binding pocket. PROTAC: ubiquitination databases record sites on it; its protein half-life has been measured; a small molecule that binds it is known.
Target class: Enzyme; Oxidoreductase
Gene: Protein-coding gene on chromosome 10 (100,529,072 to 100,559,998, forward strand). Ensembl gene ENSG00000166135.
Subcellular location: Nucleus; Cytoplasm; Cytoplasm, perinuclear region
Subcellular location (Human Protein Atlas): Nucleoplasm; Cytosol
Pathways (Reactome):
Cellular responses to stimuli: Cellular response to hypoxia
Gene Ontology:
Molecular function: [protein]-asparagine 3-dioxygenase activity; ankyrin repeat binding; carboxylic acid binding; ferrous iron binding; NF-kappaB binding; Notch binding; peptidyl-aspartic acid 3-dioxygenase activity; peptidyl-histidine dioxygenase activity; protein binding; protein homodimerization activity; RNA polymerase II-specific DNA-binding transcription factor binding; transcription corepressor activity; zinc ion binding; oxygen sensor activity
Biological process: negative regulation of Notch signaling pathway; negative regulation of transcription by RNA polymerase II; positive regulation of myoblast differentiation; positive regulation of vasculogenesis; regulation of vascular endothelial growth factor receptor signaling pathway; regulation of developmental process; regulation of signal transduction
Cellular component: cytoplasm; cytosol; nucleoplasm; nucleus; perinuclear region of cytoplasm
Genetic constraint (gnomAD): Loss-of-function variants: 18 observed, 44.18 expected, observed/expected ratio (o/e) 0.41, 90% interval 0.28 to 0.6. The upper end of that interval is the gene's LOEUF score, 0.6, which puts it in group 2 of 6, group 1 being the genes least tolerant of losing a copy. Missense variants: 315 observed, 437.94 expected, observed/expected ratio (o/e) 0.72, 90% interval 0.65 to 0.79. Synonymous variants: 146 observed, 160.25 expected, observed/expected ratio (o/e) 0.91, 90% interval 0.8 to 1.04.
Homologues: Orthologues: macaque HIF1AN (100% identical), chimpanzee HIF1AN (99% identical), pig HIF1AN (98% identical), dog HIF1AN (97% identical), mouse Hif1an (97% identical), rat Hif1an (97% identical), rabbit HIF1AN (95% identical), guinea pig HIF1AN (92% identical), tropical clawed frog hif1an (85% identical), zebrafish hif1an (79% identical). Paralogues in human: KDM8 (24% identical), HSPBAP1 (24% identical), TYW5 (19% identical), JMJD7 (16% identical).
Diseases named in the same sentence as HIF1AN in open-access papers:
HIF1AN is named in the same sentence as 29 diseases in open-access papers, as found by Europe PMC text mining. Sharing a sentence is not in itself a finding about the gene and the disease. The quoted sentences say what the papers report.
breast cancer (7 papers, 2017 to 2025). A primary or metastatic malignant neoplasm involving the breast. "In this study, we investigated the association of three polymorphic sites, RASA2 (rs16851483), CADM1 (rs12286929) and HIF1AN (rs17094222), with breast cancer risk among Chinese women based on previously identified obesity-related SNPs from the GWAS study." (PMID 29228687, 2017). "Results from the interactions between WC ≥ 80, WHR ≥ 0.85 and HIF1AN T/C genotypes also showed a significantly increased risk of breast cancer." (PMID 29228687, 2017). "In this study, we explored the interactions between candidate SNPs of RASA2 (rs16851483), CADM1 (rs12286929) and HIF1AN (rs17094222) and body fatness for breast cancer risk." (PMID 29228687, 2017). "This study provided a novel insight into the roles of obesity and gene polymorphisms of RASA2, CADM1 and HIF1AN in the development of breast cancer." (PMID 29228687, 2017). "While much studies have shown that HIF1AN gene expression is downregulated in various cancers, including breast cancer, thyroid cancer, prostate adenocarcinoma, and uterine corpus endometrial carcinoma." (PMID 41252605, 2025). "Correlation analysis between the expression of HIF1AN and Chemokines & Receptors in breast cancer at TISIDB datasets." (PMID 36816977, 2023). "The expression of HIF1AN was downregulated in most cancers such as breast cancer (BRCA), thyroid cancer (THCA), prostate adenocarcinoma (PRAD), and uterine corpus endometrial carcinoma (UCEC)." (PMID 36816977, 2023). "According to our studies, HIF1AN expression was downregulated in breast cancer females which correlated with poor prognosis." (PMID 36816977, 2023). "Surprisingly, the PAM50 test showed that the effect of HIF1AN expression on survival rates varied across different breast cancer subtypes." (PMID 36816977, 2023). "It is yet unknown how HIF1AN, clinical outcomes, and immune involvement in breast cancer (BC) are related." (PMID 36816977, 2023). "In breast cancer, HIF1AN expression has been shown to be elevated in metastatic cases." (PMID 32620123, 2020). "In this study, although the positive association between the genotypes of rs17094222 and breast cancer risk was not obtained, the joint effect of BMI ≥ 24 and HIF1AN T/C heterozygote was observed to increase the risk to develop breast cancer." (PMID 29228687, 2017). "Therefore, we concluded that HIF1AN may be a tumor suppressor with the potential to be a treatment target in women with breast cancer." (PMID 36816977, 2023). "Finally, 6 genes (GOLGB1, TMEM158, CXCL8, MCM5, HIF1AN, and TSPAN31) were selected that could optimally predict the lung metastasis risk of breast cancer patients." (PMID 33378415, 2020). "However, the variants in HIF1AN for the susceptibility to breast cancer have not been previously assessed in detail." (PMID 29228687, 2017).
ovarian carcinoma (6 papers, 2020 to 2023). A malignant neoplasm originating from the surface ovarian epithelium. "A previous report has indicated that miR-135b-5p can inhibit HIF1AN expression and improve the proliferation ability of ovarian cancer cells." (PMID 34944311, 2021). "For instance, CDR1as acts as a miR-135b-5p sponge and upregulates HIF1AN to suppress invasion and migration of ovarian cancer cells." (PMID 34221006, 2021). "Moreover, CDR1as suppresses ovarian cancer progression as miR-135b-5p sponges to upregulate HIF1AN expression." (PMID 34221006, 2021). "In ovarian cancer, circ-CDR1as was significantly lower in tumour tissues, and functioned as a sponge of miR-135b-5p to increase the expression of hypoxia-inducible factor 1-alpha inhibitor (HIF1AN), thus exerting inhibitory role on proliferation capacity of ovarian cancer cells." (PMID 31937318, 2020). "Furthermore, a comparable investigation revealed that miR-135b-5p may promote the growth of ovarian cancer cells by suppressing HIF1AN the expression." (PMID 36816977, 2023).
prostate carcinoma (3 papers, 2014 to 2024). A carcinoma that arises from epithelial cells of the prostate gland. "HIF-1AN is associated with advanced prostate cancer due to its regulatory effects on HIF-1." (PMID 25431923, 2014). "Only a handful of studies have reported deletion of the chromosomal region containing HIF1AN (encoding FIH) in glioblastoma multiforme, prostate cancers, and a small set of pediatric T cell acute lymphoblastic leukemias." (PMID 38422022, 2024). "Other six genes, including upregulated JARID2, JMJD4, and RIOX2, as well as downregulated HIF1AN, HR, and UTY were not reported in prostate cancers so far." (PMID 36776320, 2023).
keloid (2 papers, 2017 to 2023). An irregularly shaped, elevated mark on the skin caused by deposits of excessive amounts of collagen during wound healing. "Knocking down HIF1AN enhances the proliferative and migratory potentials of human keloid fibroblasts." (PMID 37854282, 2023). "Further studies demonstrated that miRNA-31 regulated proliferation, apoptosis and cell cycle of keloid-derived fibroblasts by mediating HIF1AN/VEGF signaling pathway." (PMID 29088812, 2017). "We consider that miRNA-31/HIF1AN/VEGF pathway may play a critical role in the process of keloid." (PMID 29088812, 2017). "Based on these results, our study suggests that upregulation of miRNA-31 inhibits HIF1AN expression and activates VEGF in keloid scarring." (PMID 29088812, 2017).
lymph node metastasis (2 papers, 2020 to 2021). "Here, we found TMEM161B‐AS1 and HIF1AN expression were both related to TNM stage and lymph node metastasis." (PMID 34046994, 2021). "HIF1AN (hypoxia inducible factor 1 subunit alpha inhibitor) was found to be correlated with the absence of lymph node metastasis." (PMID 33378415, 2020).
Obesity (2 papers, 2014 to 2017). Accumulation of substantial excess body fat. "Genome-wide association studies (GWAS) have indicated that gene polymorphisms in alleles of RAS p21 protein activator 2 (RASA2), cell adhesion molecule 1 (CADM1) and hypoxia inducible factor 1 alpha subunit inhibitor (HIF1AN) are associated with the risk of obesity." (PMID 29228687, 2017). "Such risk might be modified by specific polymorphisms of obesity-related genes such as RASA2 rs16851483, CADM1 rs12286929 and HIF1AN rs17094222, yielding some novel insights into breast carcinogenesis." (PMID 29228687, 2017).
renal fibrosis (2 papers, 2019 to 2020). A final common manifestation of a wide variety of chronic kidney diseases characterized by glomerulosclerosis and tubulointerstitial fibrosis. "Therefore, HIF1AN can be regarded as a critical agent implicated in the process of renal fibrosis." (PMID 30536131, 2019). "In order to validate that miRNA-184 promoted the progression of renal fibrosis by inhibiting HIF1AN expression, qRT-PCR assay was performed to determine the expression of α-SMA, GTGF, COL1A1, and COL3A1." (PMID 30536131, 2019). "In conclusion, the present study provides the novel finding that miRNA-184 plays a role in renal fibrosis by targeting HIF1AN." (PMID 30536131, 2019). "In a word, HIF1AN involves in the progression of renal fibrosis mediated by miRNA-184." (PMID 30536131, 2019). "In addition, we had a new finding that HIF1AN, a target of miRNA-184 during renal fibrosis, exerts its ability to regulate miRNA-184-induced the expression of fibrotic markers to facilitate fibrosis." (PMID 30536131, 2019). "Here, we found miRNA-184 as a critical mediator to promote the renal fibrosis by targeting HIF1AN." (PMID 30536131, 2019). "Similarly, up-regulation of miR-184 promotes renal fibrosis by binding to HIF1AN." (PMID 32545915, 2020). "Thus, miRNA-184 is an important agent to promote the fibrosis though binding to HIF1AN, and may be a promising novel target in treatment of renal fibrosis." (PMID 30536131, 2019). "Notably, miRNA-184 promoted the progression of renal fibrosis, which could be inhibited by HIF1AN." (PMID 30536131, 2019).
breast tumors (1 paper, 2023). "HIF1AN is a predictive indicator for breast tumors, and it is useful for predicting survival rates." (PMID 36816977, 2023). "proving that HIF1AN may have a role in controlling T cell fatigue in breast tumors." (PMID 36816977, 2023).
choriocarcinoma (1 paper, 2025). An aggressive malignant tumor arising from trophoblastic cells. "Hsa-miR-21-5p acts as an oncogenic miRNA in this context by suppressing HIF1AN, thus indirectly activating the HIF1A/VEGF pathway and promoting tumorigenesis in choriocarcinoma under hypoxic conditions." (PMID 40362695, 2025).
Chronic colitis (1 paper, 2023). A chronic inflammatory disease of the large intestine (colon, cecum and rectum). "Increased HIF1AN expression was associated with chronic colitis in a previous study." (PMID 36816977, 2023).
cyst (1 paper, 2014). A sac-like closed membranous structure that may be empty or contain fluid or amorphous material. "It is most likely that (membranous) CSPG4 marks definite epithelial lineage, different from that of an adult pancreatic cell and prone to cyst formation upon ‘pseudo-hypoxic’ CSPG4 overexpression in association with transforming pVHL, HIF1AN and LKB1 mutations." (PMID 24932730, 2014).
diabetic nephropathy (1 paper, 2024). "In a diabetic nephropathy human mesangial cell (HMC) model, TRG increased miR-5189-5p expression, reduced hypoxia-inducible factor 1 subunit alpha inhibitor (HIF1AN) levels, modulated the AMPK pathway, and promoted autophagy, demonstrating a protective role in response to high glucose exposure." (PMID 38542359, 2024).
fungal keratitis (1 paper, 2017). "The average ratios of the expression levels of the Hmox1, Nos3, Hif1a, Sod2, Sod3, and Gpx2 genes increased more than 2-fold (p < 0.05) at day 1 p.i. in the fungal keratitis model, whereas the expression ratios of the Hif1an and Prdx6 genes decreased more than 2-fold (p < 0.05)." (PMID 28874754, 2017).
head and neck cancer (1 paper, 2023). A primary or metastatic malignant neoplasm affecting the head and neck. "Earlier studies also showed that HIF1AN deficiency increased VEGF expression in head and neck cancer, elevated the expression of HIF1AN to suppress the oncogenic progression of head and neck squamous cell carcinoma." (PMID 36816977, 2023).
myocardial ischemia (1 paper, 2022). A disorder of cardiac function caused by insufficient blood flow to the muscle tissue of the heart. "Similarly, silenced MALAT1 reduced myocardial ischemia-reperfusion injury in rat cardiomyocytes by regulating the miR-135a-5p/HIF1AN axis." (PMID 36032150, 2022).
tumor (9 papers, 2017 to 2023). "This study is the first systematic in-clinic investigation of core correlations of HIF1AN in BC, exploring its potential molecular mechanism and function in modulating the tumor microenvironment." (PMID 36816977, 2023). "For cancer patients with HIF1AN expression, the number of clinical and pathological factors, molecular subtypes, tumor phases (phase 1, 2, 3, and 4), and lymph node phase (N0, 1, 2 and 3) were examined." (PMID 36816977, 2023). "We first assessed the expression of FIH (HIF1AN gene) across different tissues and tumor types at the transcriptional level." (PMID 37707961, 2023). "Using the GEPIA, UALCAN, TIMER, Kaplan-Meier plotter, and TISIDB datasets, a thorough analysis of HIF1AN differential expression, medical prognosis, and the relationship between HIF1AN and tumor-infiltrating immune cells in BC was conducted." (PMID 36816977, 2023). "HIF1AN was also found to be involved in immune infiltration mechanisms, to modulate the tumor immune microenvironment." (PMID 36816977, 2023). "The HIF1AN inhibits hypoxia-inducible factor 1α (HIF1α), and the downregulation of HIF1AN promotes tumor angiogenesis, cell invasion and proliferation." (PMID 38309281, 2023). "The presents of HIF1AN inhibits hypoxia-inducible factor 1α (HIF1α), and downregulation of HIF1AN promotes tumor angiogenesis, cell invasion and proliferation." (PMID 33921348, 2021). "The fundamental pathways via which HIF1AN prevents tumor growth and immunological interaction with BC are currently unknown." (PMID 36816977, 2023). "This indicate that decreased HIF1AN level may through chemokines regulate the tumor growth and apoptosis." (PMID 36816977, 2023). "Therefore, there is a need to further investigate the relationship between HIF1AN and tumor rates." (PMID 36816977, 2023). "Additionally, numerous studies have revealed that HIF1AN suppresses the growth of cancerous cells and might function as a potential tumor inhibitor in gastrointestinal and prostate cancer." (PMID 36816977, 2023). "More importantly, TMEM161B‐AS1 expression displayed positive correlation with HIF1AN in ESCC tissues, combined with previous reports about HIF1AN function, implying the potential role of TMEM161B‐AS1 in tumour glycolysis." (PMID 34046994, 2021). "Mechanistically, TMEM161B‐AS1 served as a molecular sponge by absorbing miR‐23a‐3p, a vital tumour oncogene that promotes ESCC proliferation, invasion and glycolysis by directly targeting HIF1AN and glycolysis‐related proteins." (PMID 34046994, 2021). "Starting from this observation, through bioinformatic analysis we focused our attention on miR-31-5p, which is reported to regulate the expression of HIF1AN, RhoA and RAC1 in different tumor cell lines and hMSCs." (PMID 30925808, 2019). "It is suggested that lower expression of HIF1AN is correlated with a higher level of T cell exhaustion markers, which indicates that the tumor may under a hypoxia state, the HIF1A is activated, and the T cells enter a cellular state called “Exhaustion”, they unable to clear the tumor cells." (PMID 36816977, 2023).
cancer (6 papers, 2021 to 2025). A tumor composed of atypical neoplastic, often pleomorphic cells that invade other tissues. "Nevertheless, they suggest that the role of HIF1AN in TILs attraction and cancer microenvironment through which immune cells regulate tumorigenesis, cancer development and metastasis, as well as affect the efficacy and/or resistance to chem- and immunotherapy." (PMID 36816977, 2023). "The differential expression of HIF1AN between various cancers and nearby healthy tissue was assessed on the TCGA database." (PMID 36816977, 2023). "In normal cells and cancer cells, HIF1AN was considerably reduced in BC cells, and it was related to the tissue level." (PMID 36816977, 2023). "Although HIF1AN has been well investigated in several kinds of malignant tumors, its clinical significance and possible regulatory role in immunity in breast malignancy is unknown." (PMID 36816977, 2023). "Interestingly, the findings suggested a correlation between HIF1AN in breast malignancy and PDCD1, LAG3, CTLA4, and GZMB of T cell exhaustion as well as chemokine ligand CCL2 of TAMs." (PMID 36816977, 2023). "It was shown that increased hsa-miR-21-5p maturation subsequently led to degradation of HIF1AN (HIF1A asparagine hydroxylase), an inhibitor of HIF1A, thus activating HIF1A-VEGFA signaling and promoting cancer progression." (PMID 40362695, 2025).
HIF1AN also shares sentences with these, for which no sentence is quoted: prostate adenocarcinoma (2 papers); thyroid cancer (2); uterine corpus endometrial carcinoma (2); Bardet-Biedl syndrome (1); colorectal cancer (1); congenital diaphragmatic hernia (1); Duane retraction syndrome (1); glioblastoma multiforme (1); glioma (1); head and neck squamous cell carcinoma (1); T-cell acute lymphoblastic leukemia (1); triple-negative breast carcinoma (1).